CDK4 (cyclin dependent kinase 4)
Diseases named in the same sentence as CDK4 in open-access papers (continued):
Sharing a sentence is not in itself a finding about the gene and the disease.
tumor (continued). "There are many different potential explanations, including that CDK4/6 inhibition can induce senescence, apoptosis, metabolic reprogramming and/or anti‐tumour immunity (for reviews see), but whether a common event underlies these different outcomes is unclear." (PMID 35037284, 2022). "Given that inhibition of CDK4 activity in TNBC cell lines results in BCSC differentiation and loss of self-renewal, blocking CDK4 activity in this and other tumor types is a sound approach and has resulted in the approval of several CDK4/6 ATP-mimetics for use in the clinic." (PMID 36051751, 2022). "We supposed that CDK4/6 inhibitors and radiotherapy might be a promising therapeutic combination for cancer therapy to enhance anti-tumor immune responses." (PMID 36578072, 2022). "Then, we evaluated whether the same increased anti-tumor activity demonstrated by abemaciclib in combination with lenvatinib could be achieved by inhibiting CDK4/6 with ribociclib." (PMID 35936714, 2022). "Further research is needed to understand how tumour cells escape the known resistance CDK4/6 mechanisms involving E2F transcriptional activity, tumour suppressor protein RB dependent cell division arrest and senescence stage, cyclin D dependent apoptosis, and others." (PMID 35800379, 2022). "Therefore, CDK4/6 inhibitors can inhibit Rb phosphorylation to prevent the proliferation of tumor cells." (PMID 35243562, 2022). "Interestingly, CDK4/6i significantly enhances the anti-tumor efficacy of PD-1/PD-L1 checkpoint inhibition in numerous preclinical mouse models." (PMID 35444175, 2022). "Given BRAFi+MEKi-mediated tumor cell death induces a T cell response, upfront co-treatment with CDK4/6i may be used to opportunistically improve the quality of this immune response early on." (PMID 35444175, 2022). "The immunohistochemistry shows tumor cells positive for CDK4 and MDM2." (PMID 36093467, 2022). "The complexity of senescence may limit the efficacy of anti-neoplastic agents, such as CDK4/6 inhibitors (Cdk4/6i), that induce a senescence-like state in tumor cells." (PMID 35158840, 2022). "Moreover, CDK4/6i have been reported to increase antigen presentation, helping to facilitate the anti-tumor immune response." (PMID 35158840, 2022). "In addition, CDK4 has been shown to participate in processes outside the regulation of the cell cycle leading to tumor development, including cell senescence, gene repair and metabolism." (PMID 35494047, 2022). "Even in settings where toxicities are manageable, concurrent and continuous administration of CDK4/6i with ICI may prove to be a double-edged sword in regard to anti-tumor activity." (PMID 35444175, 2022). "In an attempt to leverage this, preclinical investigators have combined several CDK4/6 inhibitors with a variety of immunotherapeutics, demonstrating superior control of tumor growth, and the generation of T cell memory which engenders resistance to tumor re-challenge." (PMID 35248122, 2022). "Consequently, the combination of CDK4/6 inhibitors with anti-PD-1/PD-L1 therapy showed an additive effect in animal tumor models." (PMID 35911672, 2022). "Together, these results demonstrate for the first time that the hydrophobic tagging-based CDK4/6 degrader has significant anti-tumor activity against TNBC and could be a potentially useful treatment strategy TNBC." (PMID 35479314, 2022). "By reversing this effect, CDK4/6 inhibitors may promote the immunologic control of gammaherpesvirus-induced tumors in addition to their direct effects on tumor cell proliferation." (PMID 35562811, 2022).
tumor (continued). "Both p15INK4b and p16INK4a bind to and inhibit CDK4 and CDK6, maintaining the growth-suppressive activity of the Rb tumor suppressor; loss or inactivation of either p15INK4b or p16INK4a contributes to the dysregulation of the CDK4/6-cyclin-Rb pathway and to the loss of cell-cycle control." (PMID 36359251, 2022). "In addition, CDK4/6 inhibitors play an important role in regulating metabolism and tumor microenvironment." (PMID 36530984, 2022). "Indeed, CDK4 inactivation led to reduced tumor development and induction of senescence in KRAS (G12V) mouse models." (PMID 35922812, 2022). "In addition to tumor-intrinsic responses, several groups have evaluated the effects of CDK4/6i on the TIME in CM." (PMID 35513054, 2022). "CDK4/6 inhibitors can induce a senescent-like cell state which could variably impact tumor growth/progression." (PMID 36119484, 2022). "Thus, Class I HDAC inhibitor MS275 and CDK4/6 inhibitor abemaciclib had synergistic anti-tumor effect and were more effective than MS275 or abemaciclib alone." (PMID 35062876, 2022). "The cyclin E/CDK2 axis is known to enhance tumor growth in addition to CDK4/6 function, which subsequently drives cell cycle progression and could potentially bypass CDK4/6 inhibition for cell cycle transition." (PMID 35884422, 2022). "This unanticipated ability of CDK4/6 inhibitors to induce DNA damage now provides a rationale to better predict responsive tumour types and effective combination therapies, as demonstrated by the fact that CDK4/6 inhibition induces sensitivity to chemotherapeutics that also cause replication stress." (PMID 35037284, 2022). "Similarly, inhibitors of the Cyclin-dependent Kinases (CDKs), such as the CDK4/6 inhibitor Palbociclib, are being used to target tumours with uncontrolled cell cycle progression, for instance, following the loss of the CDK inhibitor p16INK4a." (PMID 35301407, 2022). "Despite some limitations, including the limited sample size, long follow-up, and data concerning LDH as an indicator of tumour burden, the study brings some important knowledge to the field, showing that there are immunological effects correlated to the use of CDK4/6 inhibitor as a single agent." (PMID 36135204, 2022). "Furthermore, OTX015 exhibits synergy when combined with the CDK4/6 inhibitor abemaciclib and induced higher tumor regression than the current standard-of-care regimen of abemaciclib + fulvestrant." (PMID 35881485, 2022). "Finally, we screened a panel of 22 cancer cell lines for their response to different CDK4/6 inhibitors and we show that F9 loss-of-function confers a partial resistance to the proliferative arrest induced by CDK4/6 inhibitors in other tumour types." (PMID 35184131, 2022). "Recently, it has been discovered that the overall anti-tumor activity of CDK4/6i might not only rely on their direct anti-proliferative effects on cancer cells, but also on initiating an anti-tumor immune response." (PMID 35948546, 2022). "Notably, it has been recently shown that triple inhibition by FULV, CDK4/6i, and AKTi durably impairs BC cell growth, prevents progression, and reduces metastases of tumor xenografts resistant to the combination of CDK4/6i and FULV or FULV alone." (PMID 36045911, 2022). "Moreover, more significant tumor growth inhibition (131% TGI) was observed when ARV-471 was combined with a cyclin dependent kinase 4/6 (CDK4/6) inhibitor, significantly decreasing ERα protein levels." (PMID 35370971, 2022). "In addition, CDK4/6 inhibition is also very attractive, as it can influence the tumor microenvironment by impacting cell-mediated immunity and enhancing anti-tumor responses." (PMID 35892870, 2022).
tumor (continued). "Tumour cells with diminished endocrine signalling can bypass CDK4/6 inhibition through upregulation of the JNK pathway and showed that in cancer cells with high oestrogen signalling, potentiation of CDK4/6 activation can occur through ERBB4 and ERK upregulation and activation." (PMID 35800379, 2022). "Moreover, concurrent administration CDK4/6 inhibitor and autophagy inhibitor has reduced tumor growth in these models." (PMID 36266723, 2022). "Moreover, this benefit is maintained regardless of the duration of response to the previous CDK4/6i-based treatment or presence of CDK4/6i resistance genes in circulating tumor DNA (NCT0305675538–40)." (PMID 36071033, 2022). "However, the dose-limiting toxicities of the CDK4/6 inhibitors and the inevitable resistance of tumor cells toward them have limited their clinical application, with the exception of ER+ metastatic breast cancer." (PMID 35058574, 2022). "Therefore, the current retrospective analysis was initiated to understand the molecular mechanism of resistance to CDK4/6i by analyzing tumor genomic data acquired through routine clinical care in patients who received CDK4/6i as standard-of-care therapy." (PMID 35804935, 2022). "Moreover, small-molecule screening identified CDK4/6 inhibitors as compounds capable of enhancing T-cell activity and tumor infiltration." (PMID 36498861, 2022). "Already available results show that patients post CDK4/6i have a significantly higher tumor mutation burden compared to patients not pretreated with the same drugs (median 2.92 vs. 1.67, p < 0.0001), and higher frequency of ESR1 alteration." (PMID 35330128, 2022). "23.7% of primary tumours were CDK4 positive and 44.8% were CDK6 high." (PMID 34921235, 2022). "Early work had shown that, miR-545 levels in lung cancer tissues are downregulated and it may act as tumor suppressor sincemiR-545 mimic inhibits the cell cycle in G0/G1 phase by repressing the expression of Cyclin D1 and CDK4 genes." (PMID 36303933, 2022). "The inhibition of CDK4/6 and MEK has been linked to increased HLA-II expression in tumor cells." (PMID 35831288, 2022). "CDK4 is a key member in CDKs, which is relevant to human tumor progression." (PMID 34719318, 2021). "Moreover, combining 5‐Aza with CDK4/6i resulted in greater inhibition of AGS‐PAX6 tumor growth in mice than the single 5‐Aza treated group or CDK4/6i treated group, and this effect was augmented in the AGS‐vector group." (PMID 34459131, 2021). "According to recent reports, CDK4/6 inhibitors could not only induce tumor cell cycle arrest but could also promote antitumor immunity." (PMID 35095879, 2021). "As a consequence, inhibition of Cdk4/6 and/or activation of Cdh1 or pRb could provide a means to limit the proliferative capacity of tumor cells that have retained a functional G1 checkpoint." (PMID 33806417, 2021). "This suggests that CDK4/6i-induced effects on tumor PD-L1 expression, and subsequent synergy with anti-PD1/PD-L1 therapy, may also be relevant for RB-deficient tumor types." (PMID 34025662, 2021). "Therefore, this study aimed at investigating the expression levels of CDK4 in HCC tissues, and we have also confirmed that CDK4 has great potential as a tumor marker to predict the prognosis of patients." (PMID 34784846, 2021). "CDK4/6 inhibitors could convert HR into NHEJ mechanism in cells treated with ionizing radiation in several tumor models, which was likely attributed to the active involvement of cyclin D‐CDK4/6‐RB pathway in DDR." (PMID 34977872, 2021). "Furthermore, CDK4/6 inhibitors promote tumor cell clearance by enhancing cytotoxic T cells (CTLs) to kill tumor cells." (PMID 34395246, 2021).
tumor (continued). "Of note, it appears that upfront triple therapy (CDK4/6-BRAF-MEK-inhibitors) may have superior efficacy compared to the addition of CDK4/6 inhibitor after tumor acquisitions of BRAF/MEK inhibitors resistance." (PMID 34071228, 2021). "Further analyses of AK2 interactions with intracellular components demonstrated that AK2 recognised and interacted specifically with endogenous CDK4 and thus could be useful for detection of CDK4 within tumour cells." (PMID 34930213, 2021). "Therefore, an anti-CDK4 scFv that specifically recognizes endogenous CDK4 in tumor cells will provide a new and promising tool for achieving CDK4-targeted diagnosis and treatment of numerous types of cancers." (PMID 34930213, 2021). "It is known that the fundamental mechanism of CDKi-mediated anti-tumor activity is that inhibition of CDK4/6 decreases CDK4/6/cyclin D-induced phosphorylation of pRb, which results in the inhibition of the E2F-mediated transcription of genes involved in G1/S transition." (PMID 34831231, 2021). "Moreover, CDK6 has directly involved in transcription in tumor cells and hematopoietic stem cells in addition to the kinase activity with CDK4 in cell-cycle progression." (PMID 33925607, 2021). "Moreover, AK2 specifically recognised and interacted with endogenous CDK4 within tumour cells, thus demonstrating that we successfully obtained a specific human scFv for CDK4." (PMID 34930213, 2021). "MAPKs and CDKs can form complex kinase networks to interact and regulate cell survival and death, the targeting of which might provide a novel strategy for cancer therapy via enhancement of CDK4/6i activity and reduction of tumor resistance." (PMID 33807122, 2021). "Furthermore, the cyclin-dependent kinase 4/6 (CDK4/6) inhibitor palbociclib facilitated tumor regression in combination with H3B-6527 in a xenograft model of HCC, which indicates a potential new strategy for HCC treatment." (PMID 34006331, 2021). "Several studies have indicated that immunocyte invasion by HPV infection may contribute to the effectiveness of its treatment, whereas p16INK4A expression reflects tumor suppressor properties, as well as its role in inhibiting CDK4 and maintaining pRB." (PMID 34521948, 2021). "RB1 is a well known tumor suppressor involved in CDK4/CDK6-dependent cell-cycle regulation." (PMID 34943047, 2021). "Interestingly, CDK4/6 inhibition promotes PD-L1 surface expression on tumor cells through both RB-dependent and RB-independent mechanisms." (PMID 34025662, 2021). "These new data in fact suggest that CDK4/6 inhibitors may well cooperate with DNA or mitotic damaging agents to enhance their anti-tumor activity, if used with the proper time schedule." (PMID 34204543, 2021). "CDK4/6 regulates the cell cycle and is required for tumor initiation and progression." (PMID 33435254, 2021). "However, in recent years, the interest in identifying inhibitors of specific kinases with targeted action on tumor cells and with less toxic effects, has led to the discovery of selective CDK4/6 inhibitors." (PMID 33803309, 2021). "Furthermore, CDK4/6 inhibition is able to induce anti-tumor immunity by increasing tumor immunogenicity." (PMID 34485433, 2021). "This study found that in H1975OR, CDK4/6 inhibitor might downregulate DUB3 by inhibiting the function of CDK4, and Snail may be ubiquitinated and degraded due to the loss of DUB3 protection, thus reducing tumor invasion and metastasis." (PMID 33943009, 2021). "It should also be emphasized that the tumor microenvironment, especially in the liver, might hamper the efficacy of CDK4/6 inhibitor." (PMID 33806615, 2021).
tumor (continued). "Additionally, Goel demonstrated that CDK4 inhibition activates anti-tumor immunity; therefore it is of interest to treat STS patients with combined therapy including CDK4/6 inhibitor and immune-checkpoint inhibitor." (PMID 33686022, 2021). "In HR+, HER2− MBC patients with resistance to CDK4/6 inhibitors plus endocrine treatment, PIK3CA mutation testing on tumor tissue or circulating tumor cells is justified to select patients who could potentially benefit from alpelisib." (PMID 34885105, 2021). "Preventing resistance to CDK4/6 inhibitors from arising relies heavily on the development of biomarkers to identify what mechanisms a particular tumor could use to try to circumvent the action of these drugs." (PMID 34830174, 2021). "While there is good reason to be excited about the anti-tumor potential of therapies inhibiting both CDK4/6 and MEK, combination therapies targeting other RABL6A effectors may also have clinical efficacy in MPNSTs." (PMID 33456709, 2021). "The CDK4 pathway is dynamically regulated by the EMT status of tumor cells." (PMID 34309585, 2021). "Our data may suggest that CDK4/6 inhibitors can also be effective in patients with elevated z‐score levels as a surrogate for high tumor burden and that efficacy might be monitored frequently at low costs during treatment." (PMID 33264486, 2021). "Specifically, CDK4/6 inhibition can induce a diminished tumour immunity in various cancers." (PMID 34741389, 2021). "As in the cited study where circulating tumor cells in the plasma were analyzed, liquid biopsy could be a potential clinical approach to predict resistance to CDK4/6 inhibitors." (PMID 34885105, 2021). "Furthermore, the combination of ARV-471 and CDK4/6 inhibitor palbociclib showed great superiority over the combination of fulvestrant with palbociclib in tumor regressions." (PMID 34025443, 2021). "However, application and development of anti-tumour treatments targeting CDK4 still require more extensive and in-depth studies." (PMID 34930213, 2021). "Circulating tumor DNA (ctDNA) levels may predict response to anticancer drugs, including CDK4/6 inhibitors and endocrine therapy combinations (CDK4/6i+ET); however, critical questions remain unanswered such as which assay or statistical method to use." (PMID 33536433, 2021). "Treatment of CT26 syngeneic mouse tumors with the CDK4/6 inhibitor abemaciclib led to an increase in tumor-infiltrating T lymphocytes, and a significant upregulation of T-cell activity, as evidenced by the increased expression of T-lymphocyte activation markers (e.g., IFNG, GZMB, CCL4 and CCL5)." (PMID 33859752, 2021). "Building upon previous studies showing synergistic activity of BRAF-MEKi with ACT, we investigated whether the addition of CDK4/6i could further improve anti-tumor responses." (PMID 34944961, 2021). "Furthermore, CDK-4 is positively correlated with tumor purity in both COAD and READ while CDK-1is only positively correlated in COAD." (PMID 33732631, 2021). "Furthermore, the abundance of the TH1 chemokines CXCL-9 and CXCL-10 in the TIM was also boosted after CDK4/6i treatment, inducing the chemotaxis of T cells towards tumor sites." (PMID 33413549, 2021). "Utilizing multiple loss-of-function shRNA screens, we analyzed the effects on phenotypically different tumor subpopulations and identified cyclin-dependent kinase 4/retinoblastoma protein (CDK4/RB) as a major survival pathway in mesenchymal cell–like tumor cells." (PMID 34309585, 2021). "Moreover, CDK4-Cyclin D was found negatively regulates PD-L1 protein stability in several tumor cell lines." (PMID 34641869, 2021).